THY1 (Thy-1 cell surface antigen)
Diseases named in the same sentence as THY1 in open-access papers (continued):
Sharing a sentence is not in itself a finding about the gene and the disease.
lung adenocarcinoma (6 papers, 2017 to 2024). A carcinoma that arises from the lung and is characterized by the presence of malignant glandular epithelial cells. "The THY1 marker was used to separate the active CAF subpopulation from surgically resected human lung adenocarcinoma tissues, which was associated with cancer cell invasion, migration, and poor prognosis in lung adenocarcinoma patients." (PMID 39403603, 2024). "Furthermore, a gene expression signature inferred from THY1 + CAFs was associated with a worse prognosis for lung adenocarcinoma patients, strongly suggesting THY1 as one of the most suitable markers for CAF identification." (PMID 35884546, 2022). "THY1 + CAFs promoted cancer cell invasion and migration in a murine model of lung adenocarcinoma, localizing in the tumor periphery near actively invading tumor cells." (PMID 35884546, 2022). "Here, we used anti-THY1 antibodies to separate the active CAF subpopulation from a surgically resected lung adenocarcinoma tumor." (PMID 35884546, 2022). "Here, we postulated that the presence of Thy-1+ CAFs confers a worse prognosis in human lung adenocarcinoma." (PMID 28744021, 2017). "Because Thy-1 (CD90) marks CAFs that promote tumor cell invasion in a murine model of KrasG12D–driven lung adenocarcinoma (KrasLA1), here we postulated that human lung adenocarcinomas containing Thy-1+ CAFs have a worse prognosis." (PMID 28744021, 2017). "We first examined the location of Thy-1+ CAFs within human lung adenocarcinomas." (PMID 28744021, 2017). "Used as a probe to identify Thy-1+ CAF-enriched tumors in a compendium of 1,586 lung adenocarcinomas, the presence of the 425-gene signature predicted a significantly shorter survival." (PMID 28744021, 2017). "In contrast to the Thy-1+ gene expression signature, which was correlated with shorter survival in a subset of lung adenocarcinoma cohorts, nuclear YAP in tumor stroma was not correlated with a worse prognosis in a single patient cohort." (PMID 28744021, 2017).
psoriasis (6 papers, 2019 to 2022). An autoimmune condition characterized by red, well-delineated plaques with silvery scales that are usually on the extensor surfaces and scalp. "Compared with polymorphonuclear cells from healthy controls, polymorphonuclear cells derived from psoriasis patients have a stronger ability to adhere to Thy-1 and can be decreased by standard psoriasis treatment." (PMID 32587871, 2020). "We discovered THY1+, THY1−ACTA2high, and CXCL8+ pericytes in AD and psoriasis, mirroring those in DD." (PMID 35320046, 2022). "Similarly, Thy-1 (CD90), expressed on endothelial cells, may serve as a CR3-counterreceptor, as shown for psoriasis." (PMID 33995387, 2021).
scleroderma (6 papers, 2022 to 2025). Scleroderma is a rare autoimmune connective tissue disorder characterized by abnormal hardening of the skin and, sometimes, other organs. "Recently, it was demonstrated that THY-1-positive myofibroblasts played a pathogenic role as a biomarker of scleroderma." (PMID 37848974, 2023). "We examined Thy-1 expression in scleroderma skin and its potential role as a biomarker and pathogenic factor in animal models of skin fibrosis." (PMID 36066980, 2022). "Here, immunostaining of human scleroderma skin sections showed that DPP4+THY1+ fibroblasts accumulated in the dermal interstitial spaces and at the interface between the dermis and hypodermal adipose tissue." (PMID 39072821, 2025). "Adding to this, FB4 in scleroderma expressed higher levels of THY1 and fibroblast activation protein-α (FAP)." (PMID 37443817, 2023). "Further, FB4 in scleroderma expressed higher levels of THY1 and FAP." (PMID 37443817, 2023). "Immunostaining of the human scleroderma skin sections revealed that ECM protein MFAP5 were enriched in the interstitial spaces (white arrows) and the hypodermal interphase space between the dermis and dermal adipose tissue, where THY1 and COL1 co‐expressed." (PMID 39072821, 2025). "In contrast, activated sublining FLS were transcriptionally similar to ACTA2+ myofibroblasts and WNT5B+ fibroblasts in the colon as well as two populations of dermal fibroblasts expanded in scleroderma as compared to healthy skin (CCL19+APOE+CXCL12+ and SFRP2hiPRSS23+THY1+)." (PMID 37277655, 2023).
prostate tumor (5 papers, 2009 to 2022). "THY1 expression per positive cell in the cribriform prostate tumor microenvironment trended higher than in benign stroma but did not achieve the threshold for significance." (PMID 33600062, 2021). "Elevated THY1 (CD90) expression has previously been reported within prostate tumor stroma, but ALCAM (CD166) has not been previously investigated." (PMID 31061140, 2019).
renal fibrosis (5 papers, 2013 to 2023). A final common manifestation of a wide variety of chronic kidney diseases characterized by glomerulosclerosis and tubulointerstitial fibrosis. "Pro-fibrotic cytokines, including IL-7, IL-13, and IL-8, promote the expression of Thy-1 genes and sThy-1 release from renal interstitial fibroblasts, leading to renal fibrosis and ultimately the development of CKD." (PMID 37711613, 2023). "Enhancement of renal cGMP levels by administration of sGC stimulator BAY 41–2272 to animals with a progressive renal fibrosis at one week after induction of anti-Thy-1-induced chronic glomerulosclerosis, significantly limited tubulointerstitial fibrosis and preserved renal function." (PMID 29649334, 2018). "We found that SLC4A1, THY1, and GHR were significantly under-expressed in renal fibrosis, and PLA2G4A and EGR1 were significantly over-expressed compared with the normal group." (PMID 36120336, 2022).
thymoma (5 papers, 2000 to 2024). A neoplasm arising from the epithelial cells of the thymus. "In this report we demonstrate that the concentrationof A-MuLV injected into murine thymi influences the selection of the transformation target.Thus, concentrated A-MuLV gives rise to Thy-1+ B220- thymomas." (PMID 11293808, 2000). "THY-1 (CD90) is a highly N-glycosylated, glycosylphosphatidylinositol (GPI)-anchored cell surface protein, first identified for the recognition of thymoma cells, and was found to be expressed on various types of cells, such as mesenchymal stem cells (MSCs)." (PMID 38783357, 2024).
type 2 diabetes (5 papers, 2019 to 2024). "Diaphragm FAPs displayed upregulation of ECM and TGF-β–related expression signatures and augmentation of a Thy1-expressing subpopulation previously linked to type 2 diabetes." (PMID 38954467, 2024). "Furthermore, a specific FAP subset marked by THY1 (CD90) expression was associated with fibro-fatty degeneration in quadriceps muscles of individuals with type 2 diabetes." (PMID 38954467, 2024). "Skeletal muscle from patients with type 2 diabetes exhibits degenerative remodeling of the extracellular matrix, which is associated with a selective increase in a subset of fibrolipogenic progenitors marked by the expression of THY1." (PMID 36120336, 2022). "In this context, chronic wounds, such as those found in patients with type 2 diabetes or obese individuals, could perhaps be stimulated to heal faster by treating with soluble Thy-1." (PMID 36293394, 2022).
virus infection (5 papers, 2015 to 2024). "Thy-1 controls inflammatory cell recruitment in human and mice, and Thy-1 plays an important role in the initial stages of virus infection." (PMID 38570827, 2024). "Thy-1 moves to endothelial cell to control the initial state of virus infection, and CD11b (Mac-1) helps to Thy-1 activated to endothelial move." (PMID 38570827, 2024). "To control for the possibility that virus infection per se affects spine density, we also measured spine density in Thy1-GFP-M mice (which are Fmr1+, hence denoted “WTM”) as well as in GKO × Thy1-GFP-M (“GKOM”) mice." (PMID 37035256, 2023). "THY-1 may function through a complex setting, that would include viral gB and gH, and other cellular factors, thus links virus entry with signaling in host cells that ultimately leads to virus infection." (PMID 26147640, 2015).
brain tumor (4 papers, 2010 to 2022). "we have reported five co-regulated clusters via seven important co-expression genes (COL1A2, LUM, SPARC, THBS2, IL1B, CXCL8, THY1) interacting between five clusters of the brain tumours." (PMID 35045088, 2022). "In contrast to our data using SCLC, cell surface expression of Thy-1 was reported to be enriched in CD133+ tumour stem cells from brain tumours characterised by self-renewal, high proliferative capacity in vitro and tumour reconstitution in vivo." (PMID 20424609, 2010).
dementia (4 papers, 2023 to 2025). Loss of intellectual abilities interfering with an individual's social and occupational functions. "Our findings included well-known dementia-associated protein biomarkers, such as BMP4, CD200, MANF, PLXNB1, PLXNB3, and SMPD1 for AD and BCAN, NCAN, and THY1 for VD, as well as uncovering novel proteins associated with AD or VD." (PMID 39226887, 2024). "Another study using immunohistochemistry revealed an increased number of T cells, especially CD4 + T helper cells, in both Thy1-aSyn and dementia with Lewy bodies brains." (PMID 36715870, 2023). "Interestingly, in dementia with Lewy bodies patients and in Thy1-aSyn mice, co-localization of p38γ mitogen-activated protein kinase (MAPK) was intimately associated only with intracellular alpha-synuclein aggregates located in neuronal cell bodies." (PMID 36715870, 2023). "Comparing the average of SHAP values for core proteins for all dementia subtypes, TNR showed the highest, followed by THY1 and SMPD1, and only these three proteins presented positive values due to the low proportion of AD and VD participants in the validation cohort." (PMID 39226887, 2024). "For example, compared to AD females, AD males lacked meaningful inferred communication of the THY1, COMPLEMENT, MHC‐II, and ICAM signals, due to significant downregulation of these pathways among those with AD dementia." (PMID 41457042, 2025).
diabetic nephropathy (4 papers, 2013 to 2025). "In our animal model of diabetic nephropathy, we observed both a strong increase of Thy-1-positive cells and Thy-1 gene expression as observed in the unilateral urinary obstruction-induced (UUO) kidney fibrosis." (PMID 36768219, 2023). "In our animal model of diabetic nephropathy, we observed both a strong increase of Thy-1-positive cells and Thy-1 gene expression." (PMID 36768219, 2023). "In other insulin-sensitive, as well as fibrosis-prone organs, such as the liver, heart, and visceral adipose tissue, Thy-1 mRNA expression was not affected in this model of diabetic nephropathy." (PMID 36768219, 2023).
glaucoma (4 papers, 2013 to 2022). Increased pressure in the eyeball due to obstruction of the outflow of aqueous humor. "Thy1-YFP transgenic mice have been used in glaucoma studies as they express fluorescent neurons under the control of Thy1 promoter, a glycoprotein found on the surface of neurons including RGCs." (PMID 35645783, 2022). "BU LC MS analysis of a glaucoma and a control pool of remaining sample material supported identification of Thy-1 in glaucoma samples based on one characteristic peptide by MS/MS." (PMID 27425789, 2016). "Reanalysis of the study samples supported the presence of Thy-1 in both groups; glaucoma and control, based on raw intensities." (PMID 27425789, 2016). "In support of this, endogenous Thy1 has been shown to be down regulated in a number of studies involving mouse and rat glaucoma and has been used in other studies as a sensitive marker of RGC damage." (PMID 23977271, 2013). "In a further experiment with pooled samples of remaining tissue, Thy-1 could be identified in glaucoma samples by MS/MS analysis." (PMID 27425789, 2016). "Thy-1 related reanalysis showed that the protein is present in samples of both groups, control and glaucoma in low abundance and could be identified by two specific peptides, which correspond to the detection threshold <0.03 μg." (PMID 27425789, 2016). "We also labelled RGCs DiOlistically using the carbocyanine dyes, DiI and DiO, to control for the possibility that down regulation of Thy1 as a result of the experimental glaucoma could bias the quantification of dendritic structure in surviving cells." (PMID 23977271, 2013). "YFP is driven by the Thy1 promoter in the transgenic mice and endogenous Thy1 has been shown to be down-regulated in animal models of RGC damage or glaucoma." (PMID 23977271, 2013).
serous ovarian cancer (4 papers, 2019 to 2024). "In women with serous ovarian cancer, Thy-1 expression was associated with a significantly poorer median progression-free survival (15.8 vs. 18.3 months, P < 0.001, n = 1104), and significantly poorer median overall survival (40.1 vs 45.8 months, P = 0.036, n = 1207)." (PMID 31735168, 2019). "In a sample of 7 women with advanced (stage IIIc) high grade serous ovarian cancers and a minimum of 3 years of follow-up data, we identified differential Thy-1 RNA expression." (PMID 31735168, 2019). "To evaluate levels of RNA expression for Thy-1 in human tissue, we selected a small cohort of 7 women with stage IIIc high grade serous ovarian cancer that had undergone surgery and received adjuvant therapy with surveillance at our institution." (PMID 31735168, 2019). "We previously had examined KM Plotter data that demonstrated poorer progression-free and overall survival in women with serous ovarian cancer and high Thy-1 RNA expression." (PMID 31735168, 2019).
systemic sclerosis (4 papers, 2019 to 2023). A chronic disorder, possibly autoimmune, marked by excessive production of collagen which results in hardening and thickening of body tissues. "Skin from patients with systemic sclerosis demonstrated markedly elevated Thy-1 expression compared with controls, colocalized with fibroblast activator protein in the deep dermis, and correlated with the severity of skin involvement (modified Rodnan skin score)." (PMID 36066980, 2022). "Likewise, in systemic sclerosis, another inflammatory disease of the skin, altered fibroblasts present high Thy-1/CD90 levels." (PMID 31428610, 2019).
chronic pancreatitis (3 papers, 2014 to 2022). A chronic inflammatory process causing damage and fibrosis of the pancreatic parenchyma. "Importantly, 81% of PDAC cases stained positive for Thy1 while in normal pancreas and chronic pancreatitis cases, values were 11% and 7%, respectively." (PMID 34845270, 2021). "Overall, Thy1 neovascular immunostaining could distinguish PDAC from normal and chronic pancreatitis tissues with 90% specificity and 81% sensitivity." (PMID 34845270, 2021).
cognitive decline (3 papers, 2017 to 2021). "The (Thy-1)-h[A30P] alpha-synuclein transgenic mouse model presents cognitive decline at 12 months of age, whereas PD-like motor symptoms can be observed at 17 months." (PMID 28028735, 2017).
colon cancer (3 papers, 2020 to 2024). "Eight significantly over‐expression genes in tumour tissues (BGN, THBS2, SPARC, CDH11, MFAP2, MMP11, SPP1 and THY1) were defined as significantly signature genes that implicated in colon cancer metastasis progress." (PMID 36377223, 2022).
depression (3 papers, 2019 to 2025). "In addition, the expression level of Thy1 was shown to be significantly downregulated among the depression-susceptible group, whereas it was upregulated in the insusceptible group compared with the control group." (PMID 33627638, 2021). "Furthermore, we also noted the opposite change of Thy1 in depression-susceptible and insusceptible groups, which might be an important clue for resilience to depression." (PMID 33627638, 2021). "To assess the impact of astrocyte-derived lactate on dendritic complexity within depression- associated mPFC subregions (ACC, PrL, and infralimbic cortex (IL)), we analyzed acute brain slices from Thy1-GFP transgenic mice subjected to CSDS." (PMID 41360776, 2025). "Mice with three genotypes as WT, Ar+/− and Thy1-Ar were used to study the effect of endogenous estrogen on depression-like behaviors." (PMID 30778289, 2019). "Instead of giving estrogen treatment, our study used the newly developed brain-specific aromatase transgenic mice, Thy1-Ar, reported that elevation of brain estrogen level can reduce depression-like behavior in both sexes." (PMID 30778289, 2019).
Insulin resistance (3 papers, 2021 to 2024). Increased resistance towards insulin, that is, diminished effectiveness of insulin in reducing blood glucose levels. "On the other hand, higher bone resorption and adipogenesis in the state of insulin resistance are induced by loss of Dock 7 protein and silencing of Thy-1 expression, which contributes to loss of bone mass." (PMID 36120431, 2022). "Namely, mice with A53T expression driven by the Thy1 promoter are hypoleptinemic, have increased EE, and are resistant to high fat diet induced insulin resistance despite consuming more food." (PMID 33466831, 2021).
lupus (3 papers, 2021 to 2025). "Specifically, ligand–receptor pairs such as Thy1-(Itgam+Itgb2), Mif-(Cd74+Cxcr4), Tgfb1-(Tgfbr1+Tgfbr2), and Pecam1-Pecam1 showed higher mean expression levels in lupus mice than in DHA-treated mice." (PMID 40728997, 2025).
mesothelioma (3 papers, 2010 to 2024). A usually malignant and aggressive neoplasm of the mesothelium which is often associated with exposure to asbestos. "In vitro chemoresistance in the primary mesothelioma cell cultures was associated with increased Thy1 (CD90) expression." (PMID 29527515, 2018).
metastatic melanoma (3 papers, 2009 to 2023). A melanoma that has spread from its primary site to another anatomic site. "In this study, we determine the clinical significance of pretreatment CAF (Thy1, SMA, FAP) profiles according to both in situ cell counts and QIF protein expression in relation to immunotherapy outcome in metastatic melanoma." (PMID 31337426, 2019).
metastatic tumors (3 papers, 2017 to 2020). "For example, both MCAM and THY1, which encode cell adhesion molecules of the immunoglobulin superfamily (IgSF-CAMs), are frequently overexpressed in metastatic tumor tissues." (PMID 30102725, 2018).
pancreatic adenocarcinoma (3 papers, 2014 to 2023). "In a recent study, Thy1 (thymocyte differentiation antigen 1) was identified and validated as a new biomarker in the diagnosis of pancreatic adenocarcinoma that can be outlined by ultrasounds in mice." (PMID 38137745, 2023).
triple-negative breast carcinoma (3 papers, 2018 to 2020). An invasive breast carcinoma which is negative for expression of estrogen receptor (ER), progesterone receptor (PR), and human epidermal growth factor receptor 2 (HER2). "Based on the analysis of the bc-GenExMiner v4.4 database, CD1B, THY1 and DOCK2 were found to affect the metastatic recurrence of triple-negative breast cancer." (PMID 32867782, 2020).
urothelial bladder carcinoma (3 papers, 2021 to 2023). "On the contrary, CAFs promote tumorigenesis in urothelial bladder carcinoma via multiple markers, including alpha smooth muscle actin, CD90/Thy-1, platelet-derived growth factor receptor-alpha and -beta (PDGFR-α/-β) and especially in advanced stages significantly increased FAP-expression." (PMID 37763225, 2023).
amyotrophic lateral sclerosis (2 papers, 2011 to 2020). Amyotrophic lateral sclerosis (ALS) is a neurodegenerative disease characterized by progressive muscular paralysis reflecting degeneration of motor neurons in the primary motor cortex, corticospinal tracts, brainstem and spinal cord. "Second, we studied the effects of the chronic administration of DBT and thiamine in two mouse models: a FUS (Thy-1.FUS 1–359) transgenic mouse model of amyotrophic lateral sclerosis (ALS) and a model of ultrasound-induced stress." (PMID 32962139, 2020).